HSPA1A (heat shock protein family A (Hsp70) member 1A)
Description:
Molecular chaperone implicated in a wide variety of cellular processes, including protection of the proteome from stress, folding and transport of newly synthesized polypeptides, activation of proteolysis of misfolded proteins and the formation and dissociation of protein complexes. Plays a pivotal role in the protein quality control system, ensuring the correct folding of proteins, the re-folding of misfolded proteins and controlling the targeting of proteins for subsequent degradation. This is achieved through cycles of ATP binding, ATP hydrolysis and ADP release, mediated by co-chaperones. The co-chaperones have been shown to not only regulate different steps of the ATPase cycle, but they also have an individual specificity such that one co-chaperone may promote folding of a substrate while another may promote degradation. The affinity for polypeptides is regulated by its nucleotide bound state. In the ATP-bound form, it has a low affinity for substrate proteins. However, upon hydrolysis of the ATP to ADP, it undergoes a conformational change that increases its affinity for substrate proteins. It goes through repeated cycles of ATP hydrolysis and nucleotide exchange, which permits cycles of substrate binding and release. The co-chaperones are of three types: J-domain co-chaperones such as HSP40s (stimulate ATPase hydrolysis by HSP70), the nucleotide exchange factors (NEF) such as BAG1/2/3 (facilitate conversion of HSP70 from the ADP-bound to the ATP-bound state thereby promoting substrate release), and the TPR domain chaperones such as HOPX and STUB1. Maintains protein homeostasis during cellular stress through two opposing mechanisms: protein refolding and degradation. Its acetylation/deacetylation state determines whether it functions in protein refolding or protein degradation by controlling the competitive binding of co-chaperones HOPX and STUB1. During the early stress response, the acetylated form binds to HOPX which assists in chaperone-mediated protein refolding, thereafter, it is deacetylated and binds to ubiquitin ligase STUB1 that promotes ubiquitin-mediated protein degradation. Regulates centrosome integrity during mitosis, and is required for the maintenance of a functional mitotic centrosome that supports the assembly of a bipolar mitotic spindle. Enhances STUB1-mediated SMAD3 ubiquitination and degradation and facilitates STUB1-mediated inhibition of TGF-beta signaling. Essential for STUB1-mediated ubiquitination and degradation of FOXP3 in regulatory T-cells (Treg) during inflammation. Required as a co-chaperone for optimal STUB1/CHIP ubiquitination of NFATC3 (By similarity). Negatively regulates heat shock-induced HSF1 transcriptional activity during the attenuation and recovery phase period of the heat shock response. Involved in the clearance of misfolded PRDM1/Blimp-1 proteins. Sequesters them in the cytoplasm and promotes their association with SYNV1/HRD1, leading to proteasomal degradation. (Microbial infection) In case of rotavirus A infection, serves as a post-attachment receptor for the virus to facilitate entry into the cell.
Synonyms: HSP70-1; HSP70.1; HSP72; HSPA1; HEL-S-103; HSP70; HSP70-1A; HSP70-2; HSP70.2; HSP70I
Tractability: Small molecule: a structure with a bound ligand is known; a high-quality ligand is known; it belongs to a druggable protein family. Antibody: its Gene Ontology location is reachable by antibodies, with high confidence; UniProt places it where antibodies can reach, with medium confidence. PROTAC: ubiquitination databases record sites on it; its protein half-life has been measured; a small molecule that binds it is known. Other modalities: a drug acting on it is in phase 2 or 3 trials.
Target class: Other cytosolic protein
Chemical probes: ML346
Safety:
Unwanted effects reported when the protein is acted on. In parentheses: how it was acted on, where the effect was seen, and who reports it.
severe hypersensitivity (source: ClinPGx)
Gene: Protein-coding gene on chromosome 6 (31,815,543 to 31,817,994, forward strand). Ensembl gene ENSG00000204389.
Subcellular location: Cytoplasm; Nucleus; Cytoplasm, cytoskeleton, microtubule organizing center, centrosome; Secreted
Subcellular location (Human Protein Atlas): Annulus; Flagellar centriole; Vesicles; Calyx; Perinuclear theca
Pathways (Reactome):
Cellular responses to stimuli: Attenuation phase; HSF1 activation; HSF1-dependent transactivation; HSP90 chaperone cycle for steroid hormone receptors (SHR) in the presence of ligand; Mitochondrial unfolded protein response (UPRmt); Regulation of HSF1-mediated heat shock response
Disease: Dengue Virus Genome Translation and Replication; Viral RNP Complexes in the Host Cell Nucleus
Immune System: Neutrophil degranulation; PKR-mediated signaling
Metabolism of RNA: AUF1 (hnRNP D0) binds and destabilizes mRNA
Gene Ontology:
Molecular function: ATP binding; ATP hydrolysis activity; ATP-dependent protein disaggregase activity; C3HC4-type RING finger domain binding; cadherin binding; disordered domain specific binding; enzyme binding; G protein-coupled receptor binding; heat shock protein binding; histone deacetylase binding; misfolded protein binding; protein binding; protein folding chaperone; receptor ligand activity; RNA binding; signaling receptor binding; transcription corepressor activity; transcription regulator inhibitor activity; ubiquitin protein ligase binding
Biological process: ATP metabolic process; cellular heat acclimation; cellular response to heat; cellular response to unfolded protein; chaperone-mediated protein complex assembly; endoplasmic reticulum unfolded protein response; mRNA catabolic process; negative regulation of apoptotic process; negative regulation of cell growth; negative regulation of cell population proliferation; negative regulation of endoplasmic reticulum stress-induced intrinsic apoptotic signaling pathway; negative regulation of extrinsic apoptotic signaling pathway in absence of ligand; negative regulation of inclusion body assembly; negative regulation of mitochondrial outer membrane permeabilization involved in apoptotic signaling pathway; negative regulation of protein ubiquitination; negative regulation of transcription by RNA polymerase II; negative regulation of transforming growth factor beta receptor signaling pathway; positive regulation of canonical NF-kappaB signal transduction; positive regulation of erythrocyte differentiation; positive regulation of gene expression; positive regulation of interleukin-8 production; positive regulation of microtubule nucleation; positive regulation of nucleotide-binding oligomerization domain containing 2 signaling pathway; positive regulation of proteasomal ubiquitin-dependent protein catabolic process; positive regulation of RNA splicing; and 9 more
Cellular component: aggresome; blood microparticle; centriole; centrosome; COP9 signalosome; cytoplasm; cytosol; extracellular exosome; extracellular region; focal adhesion; inclusion body; nuclear speck; nucleus; perinuclear region of cytoplasm; protein-containing complex; ribonucleoprotein complex; vesicle; endoplasmic reticulum; ficolin-1-rich granule lumen; mitochondrion; nucleoplasm; plasma membrane
Genetic constraint (gnomAD): Loss-of-function variants: 2 observed, 4.63 expected, observed/expected ratio (o/e) 0.43, 90% interval 0.17 to 1.33. That is too few expected variants to judge how well the gene tolerates losing a copy. Missense variants: 128 observed, 221.52 expected, observed/expected ratio (o/e) 0.58, 90% interval 0.5 to 0.67. Synonymous variants: 73 observed, 91.73 expected, observed/expected ratio (o/e) 0.8, 90% interval 0.66 to 0.97.
Homologues: Orthologues: chimpanzee HSPA1B (100% identical), dog HSP70 (99% identical), pig HSP70.2 (98% identical), rat Hspa1b (97% identical), mouse Hspa1a (95% identical), mouse Hspa1b (95% identical), Caenorhabditis elegans F44E5.4 (69% identical), Caenorhabditis elegans F44E5.5 (69% identical), Caenorhabditis elegans hsp-70 (67% identical), Drosophila melanogaster Hsp110 (30% identical), Caenorhabditis elegans hsp-110 (29% identical). Paralogues in human: HSPA1B (100% identical), HSPA1L (89% identical), HSPA8 (86% identical), HSPA2 (84% identical), HSPA6 (81% identical), HSPA5 (63% identical), HSPA9 (50% identical), HSPA4 (35% identical), HSPA4L (33% identical), HSPH1 (32% identical), HYOU1 (30% identical), HSPA14 (28% identical), and 1 more.
Diseases named in the same sentence as HSPA1A in open-access papers:
HSPA1A is named in the same sentence as 168 diseases in open-access papers, as found by Europe PMC text mining. Sharing a sentence is not in itself a finding about the gene and the disease. The quoted sentences say what the papers report.
breast cancer (26 papers, 2018 to 2025). A primary or metastatic malignant neoplasm involving the breast. "There is a strong association between HOTAIR and HSPA1A, a member of the heat shock protein family A (Hsp70), in breast cancer (BRCA) tissues." (PMID 38468244, 2024). "Surprisingly, only a few studies have evaluated the association between HSPA1A status and hormone receptor status in breast cancer." (PMID 35906272, 2022). "We also found an association of HSPA1A expression with poor survival in patients with lung, colon, and breast cancers." (PMID 33456581, 2021). "Alternatively, HOTAIR induces heat shock protein family A member 1A (HSPA1A) expression, a stress-associated protein, which endows radioresistance in breast cancer." (PMID 34073224, 2021). "Our result confirmed that KIAA0100 proteins are mainly associated with microtubule networks and HSPA1A proteins in the breast cancer cell line MDA-MB-231, suggesting such association may reflect its potential functions." (PMID 29867023, 2018). "For example, the expression of HSPA1A contributes to radioresistance in breast cancer and DUSP6 regulates radiosensitivity in GB and esophageal squamous cell carcinoma." (PMID 39417309, 2025). "Most breast cancer cells (clusters 0–5) exhibited high levels of hypoxia‐related genes, including HSPA1A, MT2A, S100A11, MALAT1, and UBC." (PMID 39805002, 2025). "In breast cancer, individuals with increased serum levels of HSPA1A commonly display a higher histological grade and cell proliferation index (Ki67)." (PMID 38646439, 2024). "The 70 kDa heat shock protein, called HSPA1A, is considered as a potential biomarker for the initiation and development breast cancer." (PMID 36925638, 2023). "In this exploratory investigation serum levels of HSPA1A were increased in Brazilian women with breast cancer and there was a relationship between the HSPA1A concentration and advanced tumor characteristics." (PMID 35906272, 2022). "The 13 women with locally advanced breast cancer, > stage 2A disease, had the highest median HSPA1A level." (PMID 35906272, 2022). "In both premenopausal (26–49 years of age) and postmenopausal (≥ 50 years of age) women, HSPA1A levels were higher in White breast cancer patients than in controls (p ≤ 0.0064)." (PMID 35906272, 2022). "A study reported that the lncRNA HOTAIR enhanced radioresistance in breast cancer through the miR-449b-5p/HSPA1A axis." (PMID 35600868, 2022). "The median serum levels of HSPA1A were elevated in women with breast cancer (1037 pg/ml) compared with controls (300 pg/ml) (p < 0.001)." (PMID 35906272, 2022). "An investigation of women with breast cancer concluded that elevated expression of HSPA1A was correlated with decreased disease-free survival." (PMID 35906272, 2022). "HSPA1A is a chaperone overexpressed in a large variety of tumor lines, including breast cancer, and its expression exhibited a positive correlation with that of HOTAIR in irradiated breast cancer cells." (PMID 34804940, 2021). "For, breast cancer dataset, two genes HSPA1A and ABCB5 detected by the proposed gsslasso method were also detected by other method." (PMID 30813883, 2019). "The findings were consistent with studies on other populations and strongly suggest that further studies of serum HSPA1A in breast cancer are warranted and have the potential to contribute to improved clinical diagnoses, prognosis and treatment of this prevalent malignancy of women." (PMID 35906272, 2022). "We sought to evaluate whether the serum concentration of the 70 kDa heat shock protein (HSPA1A) was elevated in Brazilian women with breast cancer, and if levels correlated with tumor characteristics." (PMID 35906272, 2022). "Elevated extracellular expression of HSPA1A in women with breast cancer, in addition to being a marker of malignancy, suggests that this heat shock protein may participate in the initiation and/or persistence of carcinogenesis." (PMID 35906272, 2022).
breast cancer (continued). "The finding of the highest HSPA1A levels in breast cancer patients with these characteristics suggests that HSPA1A production and release into the circulation may be an indication of these factors." (PMID 35906272, 2022). "HSPA2 and HSPA1A were mainly expressed in lung cancer and breast cancer cell lines." (PMID 34712697, 2021). "All six thermogenes appear to be significantly overexpressed in breast cancer (HSPA1A, HSPA4), gliomas (DNAJB5), ovarian cancers (HSPA4, DNAJB5), pancreatic cancers (HSP90AA1), prostate cancer (HSP90AB1), thymic carcinoma (BAG1, HSP90AA1), and uterine cancers (HSPA4), as compared to normal tissue." (PMID 31814876, 2019). "In addition, HOTAIR could increase radioresistance in breast cancer by promoting HSPA1A expression through binding to miR-449b-5p in MDA-MB-231 cells." (PMID 36233075, 2022). "Other typical HSF1 targets upregulated by heat shock (e.g., HSPA1A, HSPA1B, HSP90AB1) showed higher expression levels in all HSF1high breast cancers." (PMID 36010586, 2022). "It is possible that the differential release of HSPA1A from mammary tumors that are positive or negative for these receptors is too small to be detected in the systemic circulation." (PMID 35906272, 2022). "In our initial exploratory study of Brazilian women on their first visit to a breast cancer clinic, serum levels of HSPA1A were greatly elevated in those with breast cancer as compared to those with no breast malignancy." (PMID 35906272, 2022). "Upregulation of HSPA1A was also found in PDX tumors of the colon and breast cancers." (PMID 33456581, 2021). "Elevated HSPA1A gene expression in tumor tissues is apparently not limited to breast cancer." (PMID 35906272, 2022). "In addition, even the triple knockdown of HSPA1A/B, HSPA5, and HSPA2 expression did not decrease the viability of breast cancer MDA-MB-468 cells." (PMID 32987811, 2020).
colon carcinoma (11 papers, 2017 to 2025). "The overexpression of HSPA1A chaperone was found to elevate cell motility and to upregulate the EMT biomarkers in colon cancer cells incubated in hyperglycemic condition associated with tumorigenesis." (PMID 36500393, 2022). "The gene HspA1B is one of the most prominent biomarkers for PC and HSPA1A and HSPA1B upregulation is associated with a poor survival in colon cancer." (PMID 35887223, 2022). "A study in individuals with colon cancer demonstrated that elevated HSPA1A expression was correlated with poor prognosis." (PMID 35906272, 2022). "The expression difference of HSPA1A/HSPA1B/HSPA7/HSPA9 was verified in colon cancer cell lines and colonic epithelial cells." (PMID 34765552, 2021). "Interestingly, higher HSPA1A and HSPA1B expression was previously linked to poor survival in colon cancer." (PMID 38461240, 2024). "To explore whether downregulation of HSPA1A and upregulation of HSPA9 in colon cancer were related to DNA methylation, we analyzed the methylation of HSPA1A and HSPA9 promoters." (PMID 34765552, 2021). "Inhibition of HSPA1A promoted the apoptosis of colon cancer cells." (PMID 34765552, 2021). "In addition, early reports also suggested that cell surface expression of HSPA1A in colon carcinoma cells (CX2) would increase cell recognition by the immune system, thus representing an anti-tumor effect of extracellular HSPs." (PMID 28468249, 2017). "Results showed that HSPA1A protein was decreased (P<0.001) and HSPA9 was increased (P<0.001) in colon cancer tissues." (PMID 34765552, 2021). "We found that HSPA1A promoter methylation was significantly increased and HSPA9 promoter methylation was significantly decreased in colon cancer." (PMID 34765552, 2021). "To verify the expression difference of HSPA1A/HSA1B/HSPA7/HSPA9 in the TCGA database, we compared the expression of these genes in colon cancer cells (HCT116 and HT29) and colonic epithelial cells (CP-H040)." (PMID 34765552, 2021). "The relationships between HSPA1A and HSPA9 expression and survival were validated in the GEO dataset, and the HSPA1A and HSPA9 protein expression differences between colon cancer tissues and normal tissues were validated in the UALCAN database." (PMID 34765552, 2021). "Results showed that the expressions of HSPA1A and HSPA7 were downregulated in colon cancer cell lines." (PMID 34765552, 2021). "Results showed that promoter methylation of the HSPA1A gene in colon cancer tissues was significantly higher than normal tissues (P<0.001), and methylation of HSPA9 was significantly lower in colon cancer tissues (P<0.001)." (PMID 34765552, 2021). "Colon cancer cell lines also showed increased expression of HSPA1B and HSPA9 and decreased expression of HSPA1A and HSPA7." (PMID 34765552, 2021). "Univariate regression analysis was performed to explore the correlation of HSPA1A, HSPA1B, HSPA7, and HSPA9 expression with survival in colon cancer patients." (PMID 34765552, 2021). "The results were consistent with the results from the TCGA database, showing that HSPA1A was decreased and HSPA9 was increased in colon cancer." (PMID 34765552, 2021). "In colon carcinoma cellular models (CX2), hypoxia treatment triggered a co-localization of HSPA1A with phosphatidylserine on the cell surface, which reduced cell viability." (PMID 28468249, 2017). "Methylation of HSPA1A and HSPA9 was also analyzed, and it was found that the methylation of the HSPA1A promoter was significantly increased, and the methylation of the HSPA9 promoter was significantly decreased in colon cancer tissues." (PMID 34765552, 2021). "Furthermore, GO ontology analysis was performed to screen the signaling pathways related to HSPA1A, HSPA1B, HSPA7, and HSPA9 in colon cancer." (PMID 34765552, 2021).
head and neck squamous cell carcinoma (11 papers, 2020 to 2023). A squamous cell carcinoma that arises from any of the following anatomic sites: lip and oral cavity, nasal cavity, paranasal sinuses, pharynx, larynx, and salivary glands. "For example, the lncRNA LNCAROD acts as a scaffold for the interaction between YB-1 and HSPA1A, prevents YB-1 proteasome degradation in head and neck squamous cell carcinoma (HNSCC) cells, and promotes the malignant behavior of HNSCC cells." (PMID 34272387, 2021). "Another study revealed that LNCAROD can bind with HSPA1A and YBX1 and promoted cancer progression in head and neck squamous cell carcinoma." (PMID 37597098, 2023). "LNCAROD enhanced its mRNA stability through m6A methylation modification, and a complex with HSPA1A and YBX1 promoted the progression of head and neck squamous cell carcinoma." (PMID 34336856, 2021). "Likewise, METTL3- and METTL14-mediated m6A modification of LncAROD enhanced its stability and promoted ternary complex formation with HSPA1A and YBX1, driving progression in head and neck squamous cell carcinoma." (PMID 34458149, 2021).